CCDC32 (coiled-coil domain containing 32)
Description:
Regulates clathrin-mediated endocytsois of cargos such as transferrin probably through the association and modulation of adaptor protein complex 2 (AP-2). Has a role in ciliogenesis (By similarity). Required for proper cephalic and left/right axis development.
Synonyms: C15orf57; MGC20481; CFNDS
Tractability: Antibody: UniProt places it where antibodies can reach, with high confidence. PROTAC: ubiquitination databases record sites on it.
Gene: Protein-coding gene on chromosome 15 (40,528,683 to 40,565,054, reverse strand). Ensembl gene ENSG00000128891.
Subcellular location: Membrane, coated pit
Subcellular location (Human Protein Atlas): Plasma membrane; Basal body; Centrosome; Microtubules; Primary cilium
Gene Ontology:
Molecular function: protein binding
Biological process: head development; regulation of clathrin-dependent endocytosis; cilium organization
Cellular component: clathrin-coated pit; membrane
Genetic constraint (gnomAD): Loss-of-function variants: 9 observed, 20.67 expected, observed/expected ratio (o/e) 0.44, 90% interval 0.26 to 0.76. The upper end of that interval is the gene's LOEUF score, 0.76, which puts it in group 3 of 6, group 1 being the genes least tolerant of losing a copy. Missense variants: 204 observed, 224.15 expected, observed/expected ratio (o/e) 0.91, 90% interval 0.81 to 1.02. Synonymous variants: 63 observed, 81.98 expected, observed/expected ratio (o/e) 0.77, 90% interval 0.63 to 0.95.
Gene-disease validity (ClinGen):
ClinGen rates the evidence that CCDC32 causes each of these diseases.
cardiofacioneurodevelopmental syndrome (autosomal recessive): Moderate.
Homologues: Orthologues: macaque CCDC32 (97% identical), rabbit CCDC32 (89% identical), dog CCDC32 (87% identical), pig CCDC32 (85% identical), rat Ccdc32 (84% identical), guinea pig CCDC32 (83% identical), mouse Ccdc32 (82% identical), chimpanzee CCDC32 (77% identical), tropical clawed frog ccdc32 (53% identical), zebrafish ccdc32 (43% identical).
Diseases named in the same sentence as CCDC32 in open-access papers:
CCDC32 is named in the same sentence as 8 diseases in open-access papers, as found by Europe PMC text mining. Sharing a sentence is not in itself a finding about the gene and the disease. The quoted sentences say what the papers report.
gastric cancer (2 papers, 2016 to 2025). A primary or metastatic malignant neoplasm involving the stomach. "A previous study reported that prostate cancer-associated transcript 18 (PCAT-18), a long non-coding RNA, interacted with CCDC32 as a tumor suppressor in gastric cancers." (PMID 39823827, 2025).
papillary thyroid carcinoma (1 paper, 2025). "Additionally, CCDC32/CBX3 gene fusion has also been detected in primary tumors and metastatic lesions from papillary thyroid carcinoma patients." (PMID 39823827, 2025).
cancer (2 papers, 2025 to 2026). A tumor composed of atypical neoplastic, often pleomorphic cells that invade other tissues. "Separately, studies have shown CBX3 is an oncogene for many cancers, but the function of CCDC32 in cancers remains to be elucidated." (PMID 39823827, 2025).
tumor (1 paper, 2025). "In contrast, wild-type CCDC32 (possible tumor suppressor) decreased, with the CCDC32/CBX3 gene fusion unchanged." (PMID 39823827, 2025).
CCDC32 also shares sentences with these, for which no sentence is quoted: breast carcinoma (1 paper); glioblastoma (1); hepatocellular carcinoma (1); neuroblastoma (1).